CXCR4 (C-X-C motif chemokine receptor 4)
Diseases named in the same sentence as CXCR4 in open-access papers (continued):
Sharing a sentence is not in itself a finding about the gene and the disease.
atherosclerosis (continued). "A previous study has shown that selective enhancement of CXCR4 can maintain arterial integrity, endothelial barrier function, which could contribute to novel atherosclerosis treatments." (PMID 35571620, 2022). "Recent studies described a potential and important value of CXCR4 on atherosclerosis." (PMID 35888127, 2022). "For instance, miR-126-3p delivered by EC apoptosis bodies inhibits expression of regulator of G-protein signaling 16 (RGS16) to activate C-X-C motif chemokine ligand 12 (CXCL12) and its receptor, C-X-C motif chemokine receptor 4 (CXCR4), thereby reducing atherosclerosis." (PMID 33391525, 2021). "However, in contrast to EC CXCL12 knockout, EC CXCR4 knockout caused endothelial leakage and leukocyte invasion, implying that EC CXCR4 protects against atherosclerosis by preserving endothelial integrity and barrier function." (PMID 34494495, 2021). "Because CCR6 and CXCR4 on SWM B cells potentially play a role in mediating α-gal sensitization and α-gal sensitization has previously been associated with CAD, here we explored the relationship between CCR6/CXCR4 expression on SWM B cells and atherosclerosis." (PMID 35097011, 2021). "CXCL12 and CXCR4 coordinatively play a pivotal role in atherosclerosis and arterial injury." (PMID 34552562, 2021). "Further studies have found that mature abdominal B1a cells migrate to bone marrow in a CXCR4 dependent manner, while the expression of CXCR4 on B1 cells is higher in people with smaller coronary plaque areas, which reveals a potential target immunomodulatory method that can limit atherosclerosis." (PMID 34179129, 2021). "While these preliminary results are interesting and hint towards a suitability of [68Ga]Pentixafor PET for differentiating between vulnerable and stable plaques, future research to further investigate CXCR4 biology in atherosclerosis and its clinical implications is highly warranted." (PMID 34885030, 2021). "Additionally, platelets express some functional chemokine receptors such as CCR1, 3, 4, and CXCR4, which are involved in infection, hemostasis, inflammation, and even in the development of atherosclerosis." (PMID 34425822, 2021). "However, miR-126 modulates C-X-C chemokine receptor type 4 (CXCR4) protein levels during atherosclerosis." (PMID 31941032, 2020). "This might indicate increasing recruitment of leukocytes by interaction with CXCR4, which is responsible for pro-inflammatory reactions during atherosclerosis progression." (PMID 31004184, 2019). "Notably, CXCR4 knockdown/knockout in bone marrow or in vascular wall cells aggravates the progression of atherosclerosis in mouse models." (PMID 30890702, 2019). "Accordingly, Cxcr4 expression in the BM cells of aged ApoE−/− mice was also decreased, and BM cell engraftment was impaired which may contribute to the progression of atherosclerosis in ApoE−/− mice." (PMID 31385396, 2019). "In atherosclerotic plaque tissue, CXCR4 expression might be used as a surrogate marker for inflammatory atherosclerosis." (PMID 31004184, 2019). "In particular, previous studies have demonstrated that the use of statin therapy for atherosclerosis could induce significant downregulation of the expression of CXCR4 on monocyte subsets." (PMID 28932900, 2018). "This evidence of CXCR4 biodistribution combined with our imaging results might support the concept of using CXCR4 as a biomarker to characterize inflammatory atherosclerosis." (PMID 28932900, 2018). "In functional perspective of inflammatory activity and CXCR4 association during atherosclerosis progression, the oxidized low-density lipoprotein (Ox-LDL) could have significantly induced CXCR4 expression in the macrophage." (PMID 28932900, 2018). "In conclusion, our data implicate the CXCR4 rather than VEGF-C/D axis in atherosclerosis associated lymphangiogenesis and identified the regulatory role of adventitial lymphatics in plaque T-cell homeostasis." (PMID 28349940, 2017).
atherosclerosis (continued). "SDF-1/CXCR4 biological axis consisting of SDF-1 and its receptor CXCR4 induced CD34+ stem cells to differentiate into macrophages and foam cells, which later caused the atherosclerosis." (PMID 26074989, 2015). "SDF-1/CXCR4 biological axis is probably one of the main targets of intervening atherosclerosis." (PMID 26074989, 2015). "A latest study shows that atherosclerosis was related to SDF-1/CXCR4 biological axis." (PMID 26074989, 2015). "Here, we aim to provide an overview of in vitro, animal and patient observations that may provide insight into the (cell type-specific) effects of CXCR4 signaling on native atherosclerosis, injury-induced restenosis and MI." (PMID 24966838, 2014). "Further research is definitively needed to improve phenotypical and functional characterization of vascular progenitor cell subsets in context of atherosclerosis before a role of the CXCR4/CXCL12 axis in their mobilization and potential functions in this pathology can be investigated in detail." (PMID 24966838, 2014). "Since CXCR4 is conserved across species, understanding how this chemokine receptor functions in the mouse may explain its role in human atherosclerosis." (PMID 24741577, 2014). "CXCR4 in native atherosclerosis: cell type-specific functions?" (PMID 24966838, 2014). "MIF not only interacts with CD74, but also engages in high affinity interactions with the chemokine receptors CXCR2 and CXCR4 to drive inflammatory leukocyte recruitment processes and may mediate the inflammatory pathogenesis of experimental atherosclerosis." (PMID 22506003, 2012). "The exact role of CXCR4/SDF1 in atherosclerosis is yet unknown." (PMID 34062730, 2021). "Moreover, SDF-1 and CXCR4 may affect native atherogenesis by modulating atherosclerosis-relevant cellular functions." (PMID 33287461, 2020). "Vascular CXCR4 could limit atherosclerosis by maintaining arterial integrity." (PMID 29581828, 2018). "Due to these controversial concepts of CXCR4 functions in atherosclerosis, a systemic study was proposed to reveal the expression of CXCR4 on different types of plaque considering the specific distribution of CXCR4 proteins that could serve as an efficient biomarker for atherosclerosis imaging." (PMID 28932900, 2018). "This means enhancing arterial CXCR4 might open novel therapeutic options in atherosclerosis." (PMID 29581828, 2018). "Besides these effects on progenitor cells, mediating beneficial effects on atherosclerosis, CXCL12/CXCR4 may also influence disease development by influencing various atherosclerosis-related cells." (PMID 26257740, 2015). "In addition to a role for CXCR4 through progenitor cell mobilization, CXCR4 may affect native atherogenesis by modifying atherosclerosis-relevant cellular functions." (PMID 24966838, 2014). "For example, the binding of CXCR4 to CXCL12 promotes macrophage autophagy through the PI3K/AKT/mTOR pathway, which alleviates atherosclerosis and improves myocardial structure." (PMID 40535169, 2025). "Blockade of CXCR4 can inhibit the activation of CXCR4 after binding with CXCL12 and regulate autophagy through the PI3K/AKT/mTOR pathway to improve and reduce atherosclerosis and improve cardiac structure." (PMID 40535169, 2025). "Over the past two decades, miRs have been identified as key regulators of the pathophysiological processes involved in atherosclerosis such as signaling (NF-κB, MAPK, SOCS, SDF-1/CXCR4, TGF-β, BMP, TLR) and lipid homeostasis pathways." (PMID 38531978, 2024). "Endothelial cell receptors such as C-X-C chemokine receptor type 4 (CXCR4) and atypical chemokine receptor 3 (ACKR3) can be introduced as new targets for the treatment of atherosclerosis." (PMID 37686238, 2023). "While CXCL12 is considered to act primarily as a proatherogenic chemokine, activation of the CXCL12/CXCR4/CXCR7 axis can in fact lead to both the progression and stabilization of atherosclerosis." (PMID 36077592, 2022).
atherosclerosis (continued). "In addition, CXCR4 could be involved in the development of atherosclerosis by regulating macrophage migration inhibitor (MIF) and macrophage formation, thereby affecting leukocyte recruitment and inflammatory responses, suggesting that CXCR4 may be a therapeutic target for atherosclerosis." (PMID 35607269, 2022). "Previous work demonstrated CXCR4 and CXCR7 under inflammatory conditions by focusing on atherosclerosis and ischemic cardiac diseases." (PMID 34948374, 2021). "In particular, CXCR4, ICAM-1, Tumor Necrosis Factor Alpha-Induced Protein 3 (TNFAIP3), and Caspase-8 (CASP8) genes that present a role in atherosclerosis development at different level and with different functions were considered." (PMID 30356351, 2018). "Lastly, miR-126a-3p has also a regulatory role for the expression of CXCL12 via the inhibition of CXCR4 by RGS16, a signaling pathway that is involved in atherosclerosis and inflammation." (PMID 26956024, 2016). "The upregulation of endothelial CXCL12 mediated by apoptotic body-derived miR-126-3p in early atherosclerosis reduces lesion formation by diminishing the lesional macrophage content and increasing SMC content in a CXCR4-dependent process." (PMID 26001902, 2015). "The extent of atherosclerosis in aorta of apoE−/− mice in AsIV group was significantly lighter than that in model group, and the SDF-1 and CXCR4 expression of aorta reduced, showing statistical significance (P < 0.05)." (PMID 26074989, 2015). "This suggests potential different roles of CXCR4 and its ligand CXCL12 in atherosclerosis through interplay of CXCR4 with MIF." (PMID 24966838, 2014). "Blocking CXCR4 can promote autophagy in macrophages, alleviate atherosclerosis, improve myocardial structure, reduce the severity of coronary artery disease, and reverse atherosclerosis induced by Chlamydia pneumoniae infection by blocking TLR2/CXCR4." (PMID 40535169, 2025). "Thus, KGs of NK cells for hawthorn's effects on the PVAT microenvironment of atherosclerosis were JUN, CXCR4, CD36, GNLY, and FABP4." (PMID 40824771, 2025). "CXCR4-specific PET tracer, 68Ga-Pentixafor, was initially developed for cancer imaging, but also correlated with histologic regions immunostained for CXCR4 and macrophage-specific marker in animal atherosclerosis model." (PMID 38229205, 2024). "Thus, species-specific mechanisms, including, e.g., the observed discrepancies in the atherosclerosis development pathway involving CCR2 and CXCR4 signaling, should be taken into account in future research." (PMID 35737302, 2022). "Specific temporal and spatial modulators of CXCL12, CXCR4, and ACKR3, in addition to specific modulators of downstream signalling, should be explored to suppress their unwanted action in the pathogenesis of atherosclerosis and to enhance their desirable effects." (PMID 34494495, 2021). "In addition to ACKR3, CXCR4 enhances ox-LDL uptake and foam cell formation and promotes atherosclerosis." (PMID 34494495, 2021). "After one week, the expression in the chemokine receptors CXCR4, CCR8, CCR5, and CCR2, which are all known to play an important role in inflammation and atherosclerosis development, was analyzed on the surface of various leukocyte subsets in the blood and spleen using flow cytometry." (PMID 34884827, 2021). "CXCR4 heterodimerizes with other receptors, such as CXCR3, the Na+/H + exchanger regulatory factor 1 (NHERF1), CCR7, CCR2, CCR5, α1-AR and opioid receptors, resulting in differential signalling; however, their roles in atherosclerosis are still uncertain." (PMID 34494495, 2021). "However, this review focuses specifically on the role of CXCR4 and CXCR7 (ACKR3) receptors, their complex mutual relationship and their interaction with the ligand CXCL12 (SDF-1) in atherosclerosis." (PMID 34494495, 2021). "SDF1/CXCR4 axis and MMP12 involvement in atherosclerosis development suggests that they could be possible atherosclerotic targets." (PMID 34062730, 2021).
atherosclerosis (continued). "Additionally, CXCR4 and CXCR7 were shown to play a detrimental role in inflammatory conditions like atherosclerosis, chronic hypoxia-related pulmonary hypertension, and ischemic cardiac disease." (PMID 32210974, 2020). "The protective effects of AsIV in atherosclerosis injury may be related to AsIV downregulation of CD40L, PAC-1, and CXCR4 expression by blocking the CD40-CD40L system." (PMID 26074989, 2015). "The effects of astragaloside IV on atherosclerosis in high-fat diet apoE−/− mice may be through platelet activation and SDF-1/CXCR4 biological axis." (PMID 26074989, 2015). "Therefore, astragaloside IV plays a role in atherosclerosis of high-fat diet apoE−/− mice by regulating blood lipids, CD40-CD40L system, and SDF-1/CXCR4 biological axis probably." (PMID 26074989, 2015). "We concluded that the protective effects of AsIV in atherosclerosis injury may be related to regulating blood lipids, CD40-CD40L system, and SDF-1/CXCR4 biological axis." (PMID 26074989, 2015). "Recent observations showed that hyper-activation and life prolongation of neutrophils through knocking out CXCR4 affect progression rather than initiation of atherosclerosis." (PMID 26090792, 2015). "All of these cells play distinct roles in the pathophysiology of atherosclerosis, but not much is known about the precise role of CXCR4 in individual cellular responses." (PMID 24966838, 2014). "In the context of atherosclerosis, interference with MIF binding to both CXCR2 and CXCR4 by using a MIF blocking antibody interfered with MIF’s pro-atherosclerotic functions, while it would leave the protective homeostatic functions of the CXCL12-CXCR4 axis preserved." (PMID 23720662, 2013). "CXCR4 is one of the specific receptors for CXCL12, and its activation upon binding with CXCL12 plays a role in signal transduction related to inflammation, chemotaxis, survival, and proliferation, with high expression of CXCR4 being closely related to the stability of atherosclerosis." (PMID 40535169, 2025). "CXCR4, the specific receptor for CXCL12, is expressed in the vascular cells and macrophages and plays a crucial role in leukocyte recruitment into vessel walls and monocyte–macrophage differentiation, as well as macrophage polarization, during the development of atherosclerosis." (PMID 36670934, 2022). "Considering the relevant role of the CXCL12–CXCR4 axis in vascular homeostasis and the potential of EPCs and SMCs to release CXCL12 and express CXCR4, we analyzed the engagement of the CXCL12–CXCR4 axis in various modes of EPC–SMC interaction relevant for injury- and lipid-induced atherosclerosis." (PMID 35055054, 2022). "Moreover, the CXCL12/CXCR4 interaction activates the GSK-3β/β-cateninT120/TCF21 signalling pathway to inhibit ABCA1-dependent cholesterol efflux from macrophages to Apo-A1 and aggravate atherosclerosis." (PMID 34494495, 2021). "However, it contains several CAD candidate genes (e.g., IGFR1) and their immediate neighbors (e.g., CXCR4) that are druggable, have atherosclerosis phenotypes in mice, and act in a non-toxic tissue." (PMID 29467471, 2018). "Furthermore, blockade of MIF (macrophage migration inhibitory factor) but not of canonical ligands of CXCR2 or CXCR4 in mice with advanced atherosclerosis led to plaque regression and reduced monocyte and T-cell content in plaques." (PMID 21188276, 2010). "In addition, the combination of CXCR4 and its alternative ligand macrophage inhibitory factor (MIF) plays an important role in the recruitment of leukocytes into the intima of vessel walls after endothelial injury, a process which is crucial for the progression of atherosclerosis." (PMID 28932900, 2018). "CXCR4 expression (mRNA, protein) was reported on platelets and although platelets lack nuclei and many organelles and are mainly known for their important role in blood coagulation, their impact on immunological and inflammatory responses, in particular atherosclerosis, should not be underestimated." (PMID 24966838, 2014).
atherosclerosis (continued). "On the other hand, macrophage migration-inhibitory factor (MIF), a non-cognate ligand of CXCR4 as well as of CXCR2 and the CD75–CD44 complex, mediates atherosclerosis in a B-cell-dependent manner." (PMID 40986007, 2025). "Here, the authors have designed a peptide-based ectodomain mimic of the chemokine receptor CXCR4 that selectively targets MIF but not CXCL12 and blocks experimental atherosclerosis in vivo." (PMID 33239628, 2020). "The ubiquitously expressed chemokine, macrophage migration inhibition factor (MIF) was demonstrated as a noncognate ligand of CXCR4 (and CXCR2), shown to facilitate leukocyte recruitment during inflammatory diseases such as atherosclerosis." (PMID 25283599, 2015).